WNT5A (Wnt family member 5A)
Diseases named in the same sentence as WNT5A in open-access papers (continued):
Sharing a sentence is not in itself a finding about the gene and the disease.
cancer (continued). "Interestingly, the JAK-STAT signaling pathway, associated with cancer progression, was attenuated in MCF-7/Wnt5a (+) cells." (PMID 34047951, 2021). "In consequence, it was evaluated whether WNT5A levels correlated with TEAD target gene expression in the cancer types where a moderate to strong correlation was observed, using GEPIA." (PMID 33643710, 2021). "Also, a hexapeptide inhibitor of Wnt5a signaling, Box5, has been employed in some cancer studies, opening a new opportunity to explore the role of non-canonical Wnt signaling in GC." (PMID 33869179, 2021). "Several studies have confirmed that WNT5A promotes cytokine expression in cancer cells." (PMID 33790866, 2021). "Although one article has shown previously that WNT5A is a YAP/TEAD target gene, there is a need for further evidence supporting this regulatory relationship, because a possible YAP/Wnt5a regulatory circuit might have profound implications for cancer biology." (PMID 33643710, 2021). "Additionally, cancer cells can become dormant and evade therapy, in part due to regulation by Wnt5A." (PMID 34685470, 2021). "Experimental blocking of Tyrosine‐protein kinase transmembrane receptor (ROR2) receptors reversed the positive effect of WNT5A in cancer metastases and may induce dormancy in bone in a WNT5A/ROR2‐dependent manner." (PMID 33639039, 2021). "WNT5A-induced signaling plays a crucial role in this cancer type." (PMID 34702444, 2021). "Previous studies have shown that Wnt5a/β-catenin signaling participates in the cell survival, proliferation, cycle, migration, invasion, metastasis, apoptosis, and multidrug resistance of various cancers." (PMID 33858426, 2021). "Cancer-related cytokines, such as Tnf, as well as Wnt5a, an important mediator of an epithelial to mesenchymal transition (EMT) process and previously shown to be rapidly induced by NF-κB, are both successfully inhibited by either pre- or post- topical administration of BAY 11-7082." (PMID 32934775, 2020). "Nevertheless, lessons from studies about Disheveled and Wnt5a in GC might shed light on the mechanisms of Wnt signaling in other cancer types." (PMID 32195251, 2020). "RhoA could promote focal adhesion and regulates some cancer cell contractility, leading to cell migration, but blocking RhoA activity of RhoA could significantly inhibition the migration in wnt5a-induced cells." (PMID 32192495, 2020). "In effect, WNT5A is involved in cytoskeleton remodeling, tissue polarization, cell migration and axon guidance in healthy tissues and promotes migration and invasion in cancer cells." (PMID 33178184, 2020). "Therefore, a deeper understanding of the biological functions of Wnt5a in cancer is highly desirable." (PMID 32195251, 2020). "The higher level of WNT5A mRNA expression is elevated in most cancers." (PMID 32181818, 2020). "Lastly, Wnt5a/b silencing was found to impair cancer cell proliferation." (PMID 33080952, 2020). "Again, this observation has suggested a suppressive role of Wnt5a in cancers." (PMID 33080952, 2020). "The role of Wnt5a has been studied in several cancer types, providing valuable insights into the possible mechanisms by which Wnt5a might influence cancer cell behavior." (PMID 32195251, 2020). "Comprehensive overviews of Wnt5a in cancer have been published elsewhere." (PMID 32195251, 2020). "It has been shown that Wnt5a can promote cytokine expression in cancer cells." (PMID 31510045, 2019). "Mutations of WNT5A have been shown to associate with cancer development, possibly through noncanonical WNT signaling pathways." (PMID 31382613, 2019). "Wnt5a is a signalling protein mainly involved in developmental processes and cancer." (PMID 31098409, 2019).
cancer (continued). "In healthy ovaries, Wnt5A expression is significantly higher than in those with diagnosed cancer." (PMID 31756998, 2019). "WNT5A has also been shown to be involved with cancer cell metabolism and inflammation." (PMID 31382613, 2019). "Besides the well-known activity of VEGF-A on angiogenesis, Wnt5A signaling is emerging as a major mediator in cancer progression, regulating cancer cell invasion, metastasis and metabolism." (PMID 29849945, 2018). "Furthermore, there is an unclear picture with regard to the functional relevance of macrophage-derived WNT5A in cancer." (PMID 30171384, 2018). "The mechanism of malignant transformation by Wnt5a has been studied in a variety of cancers." (PMID 29765514, 2018). "Binding of Wnt5a to ROR1 promoted cancer cell survival and metastasis." (PMID 29856777, 2018). "Deregulated WNT5A/ROR2 signaling appears to be of great importance in cancer." (PMID 29930766, 2018). "In addition, EBV-associated carcinomas, such as NPC, which are undifferentiated tumors that carry a latent viral infection, have been associated with increased LEF1 and WNT5A mRNA levels." (PMID 29535816, 2018). "Among the nine cancer cell lines, expression levels of Wnt5a mRNA were quite varied." (PMID 28859077, 2017). "Wnt5a is known as a typical non-canonical and Wnt protein is associated with the progress and development in many malignant tumors." (PMID 29054966, 2017). "Interestingly, Wnt5a can act as a cell proliferation inhibitor in many cancer cells and mouse B cells, suggesting a cell-cycle suppressor role for Wnt5a in some cell types." (PMID 29033786, 2017). "WNT5A promoted cancer cell invasion in a receptor-mediated endocytosis-dependent manner." (PMID 29069742, 2017). "Interestingly, the combination of both, Ror2 overexpression and additional stimulation with its ligand Wnt5a (pRor2 + Wnt5a condition), was able to even further enhance cancer cell invasion compared to the Ror2 overexpression alone." (PMID 28695110, 2017). "All these properties, among others, suggest that Wnt5a is a cancer-promoting molecule." (PMID 28320399, 2017). "A correlation between Wnt5a/Ror2 and pathological grade suggests that Wnt5a/Ror2 signaling pathway could play a role in the aggressiveness of this cancer, perhaps promoting the EMT and metastasis process." (PMID 28427201, 2017). "Distinct expression of WNT5A has been reported in various cancers." (PMID 29069720, 2017). "The expression of CTHRC1 and the positive correlation between Wnt5a/Ror2 and pathological grade suggests that the Wnt5a/PCP signaling pathway could play a role in the aggressiveness of this cancer." (PMID 28427201, 2017). "Our group has identified phenylmethimazole (C10), an inhibitor of pathologic TLR3 signaling/expression, and shown that C10, by virtue of inhibiting the TLR3/Wnt5a pathway is significantly efficacious in in-vitro and in-vivo models of different cancers and auto-immune diseases." (PMID 29371911, 2017). "Consistent with the characterized infiltration of macrophages in inflammation and cancer, macrophage-derived Wnt5a has been proved to be involved in human inflammatory diseases and cancers, mainly by inducing pro-inflammatory cytokine release, angiogenesis and lymphangiogenesis." (PMID 27608847, 2016). "A reasonable speculation is that Wnt5a may in part mediate the action of TAMs on cancers, and more studies are needed to answer these questions." (PMID 27608847, 2016). "In aggregate, these data suggest that Wnt5a signaling could be an attractive target to enhance cancer cell response to chemotherapeutic drugs." (PMID 27571105, 2016). "The opposing roles for WNT-5A in cancer are intriguing and are matter of intense investigation." (PMID 26514730, 2016). "First, the relationship between miR-101b and COX2 has been previously describe in several cancer cell lines and tumors, and we want to determine whether this regulation is conserve in hippocampal neurons and if it is regulated by Wnt-5a." (PMID 26895946, 2016).
cancer (continued). "WNT5A is often downregulated in leukemia, colorectal, and esophageal cancers." (PMID 26978652, 2016). "Studies have suggested a broader function for WNT-5A in cancer than just cell growth and invasion." (PMID 26514730, 2016). "Overall, these data suggest that inhibition of Wnt5a signaling may represent a strategy to reduce metastasis in many cancer types." (PMID 27571105, 2016). "Thus, not only the downstream signaling but also the abundance of specific isoforms can contribute to the differential effects of WNT-5A in cancer." (PMID 26514730, 2016). "As summarized above, the role of Wnt5a in cancer is varied and complex." (PMID 27571105, 2016). "In recent years, the interaction between ROR2 and Wnt5A in cancer has received great attention." (PMID 28536612, 2016). "Interestingly, WNT-5A can drive metabolic reprogramming in cancer cells by inducing lactate dehydrogenase 5 (LDH5) leading to an increase in anaerobic glycolysis." (PMID 26514730, 2016). "Here, we define WNT5A, a non-canonical Wnt ligand implicated in epithelial differentiation, repair, and cancer, as a direct transcriptional target that is activated by KLF4 in squamous epithelial cells." (PMID 27184424, 2016). "The role of Wnt5a in different cancers is context-dependent." (PMID 26942462, 2016). "However, a constitutive expression or increased expression of Wnt5a and its receptor Ror2 is involved in enhanced invasive and metastatic properties of many cancer types, suggesting an oncogenic role of Wnt5a/Ror2 signaling in tumorigenesis." (PMID 27895670, 2016). "Up-regulation of WNT5A has also been reported in cancers of the lung, breast, and stomach." (PMID 25823923, 2015). "Cell migration and invasion were also suppressed in Wnt5a-, Ror1-, Ror2-, or Fz2-depleted HeLaS3 and A549 cells, suggesting that both cell proliferation and migration capabilities of these cancer cells depend on Wnt5a signaling through its receptors." (PMID 25622531, 2015). "Recently, it was reported that Wnt5a is also implicated in cancer cell proliferation, but the mechanism was not clear." (PMID 25622531, 2015). "Interestingly, Snail, CD44, G3BP2, and YAP1 are targets of Wnt5A, a gene involved in invasion and metastasis of many cancers, that is regulated by NF-κB signaling pathway." (PMID 25738332, 2015). "The expression of the two Wnt5a isoforms is highly variable among individual cancer cell lines." (PMID 25779663, 2015). "Wnt5a and Wnt receptor mRNA levels varied among cancer cell lines." (PMID 25622531, 2015). "Moreover, S-allylcysteine, another sulfur containing ingredient of garlic, in humanepithelial cancer cell line A2780, was demonstrated to inhibit migration and considerablylowered proteins involved in metastasis and growth including Wnt5a, p-AKT and c-Jun." (PMID 26889365, 2015). "Wnt5a expression was previously believed to be associated with cancer cell motility but not proliferation." (PMID 25622531, 2015). "However, the present study suggests that the endocytosis-independent mechanism exists in the β-catenin-independent pathway to regulate Wnt5a-induecd cancer cell proliferation." (PMID 25622531, 2015). "Using the monoclonal antibody, we demonstrated that Wnt5a stimulates both invasion and proliferation in certain types of cancer cells and that these cellular functions are distinctly regulated by receptor-mediated endocytosis-dependent and -independent manners." (PMID 25622531, 2015). "The essential roles of WNT5A in macrophage-induced cancer invasiveness is also reported." (PMID 25823923, 2015). "Therefore, Wnt5a exhibits metastasis-promoting activities in several types of cancer through different signaling pathways." (PMID 24944588, 2014). "Interestingly, we found that only a previous history of cancer had a statistically significant (P ≤ 0.01) effect on the level of Wnt5a present in the serum." (PMID 24346141, 2014). "In the present study, we analyzed wnt3a and wnt5a to determine their roles in cancer progression." (PMID 24564183, 2014).
cancer (continued). "Considering these data, the exact role of wnt5a in cancer is unclear." (PMID 24564183, 2014). "Hypermethylation of the CCND2, ESR1 and WNT5A loci has been reported in various cancer types." (PMID 24586797, 2014). "Otherwise, as recently reported in human cancers, Wnt5a/Ror2 signaling may up-regulate the expression of matrix metalloproteinases (MMPs) such as MMP1, MMP2, and MMP13 to increase cell invasiveness." (PMID 25211363, 2014). "For example, there are several proteins (e.g., WNT5A, RACK1, SIRT1 and several F-box proteins) whose expression levels appear to correlate with the risk to acquire certain cancers, yet the same proteins have been observed to confer protection against cancers in other paradigms." (PMID 25453033, 2014). "In a previous study, evidences indicated correlation between Wnt5A and cancer drug resistance." (PMID 25401518, 2014). "The non-canonical signaling involves numerous cellular pathways, all of them β-catenin-independent; however, based on the specific Wnt receptors present, Wnt5a can inhibit or promote β-catenin dependent signaling, which results in contradictory roles of Wnt5a in cancer." (PMID 23947922, 2013). "Interestingly, the expression differed significantly between them, with one of the cancer cell lines expressing much higher levels and the other expressing much lower levels of Wnt5a mRNA in comparison to the normal urothelial cell line." (PMID 23947922, 2013). "The mechanism by which WNT5A achieves these distinct activities in cancers is poorly understood." (PMID 24260410, 2013). "Differences in the WNT receptor repertoire, and hence in the signaling pathways triggered by WNT5A, could explain these opposing activities of WNT5A in cancer." (PMID 24260410, 2013). "Wnt-5a has been demonstrated to exert differential effects on cancer development." (PMID 24351810, 2013). "Because of its involvement in both canonical and non-canonical signaling pathways, dysregulation of Wnt5a within the cell has been associated with development and progression of several cancers." (PMID 23342259, 2012). "Evaluation of Wnt5a protein expression to identify low-grade cancers with favorable outcome may thus be useful to avoid overtreatment in this group of patients." (PMID 23342259, 2012). "The second main Wnt5a-dependent pathway is the calcium-dependent signaling pathway, which could have an oncogenic effect by stimulating cancer cell invasion." (PMID 22655072, 2012). "Cancer tissues from most patients (82%) showed a homogenous strong cytoplasmic immunostaining, whereas a majority of benign tissues (65%) showed weak immunoreaction supporting that an up-regulation of Wnt5a protein occurs in cancer tissue." (PMID 22039506, 2011). "In addition, Wnt5a knockdown by si-RNA in 22Rv1 cancer cells also resulted in increased invasion of these cells." (PMID 22039506, 2011). "In addition, some MMPs including MMP-1, MMP-2 and MMP-13 are involved in Wnt-5a mediated invasion of cancer cells." (PMID 21998657, 2011). "WNT5A mRNA displayed a similar magnitude of change (∼50 fold) in 1542-CP3TX cancer cells compared to normal 1542-NPTX cells, whether measured using oligoarray or real time PCR." (PMID 20454608, 2010). "As ROR2 and WNT5A functions are intimately associated--indeed, ROR2 knockout mice phenocopy most of alterations seen in WNT5A knockout mice --ROR2 and WNT5A might also have parallel or complementary roles in cancer." (PMID 20591152, 2010). "Taken together the human tissue and cell line data suggest that Wnt5A protein is expressed in normal (or benign) tissue but its expression is dramatically increased in malignant (cancer) prostate tissue and this change is reflected in the cell lines used in this study." (PMID 20454608, 2010). "We used myristoylated autocamtide-2-related inhibitory peptide (AIP), an inhibitor of CaMKII, and recombinant Wnt5A protein (to activate Wnt signaling) in normal and cancer cells to test these hypotheses." (PMID 20454608, 2010).
cancer (continued). "This review summarises our current understanding of Wnt-5a and cancer." (PMID 19603030, 2009). "The possibility of interaction between these two pathways may explain in part the uncertainties of the role of Wnt-5a in cancer." (PMID 19603030, 2009). "Wnt-5a has ample opportunity, therefore, to influence cancer development." (PMID 19603030, 2009). "This ability of Wnt-5a to promote cell movement has crucial implications for cancer progression." (PMID 19603030, 2009). "Furthermore, WNT5A is a potential prognostic marker for cancer progression." (PMID 35595735, 2022). "In addition, the expression of WNT5A in different types of cancers and TAMs remains controversial." (PMID 35847885, 2022). "However, our results indicate that PRDM1-induced non-canonical Wnt5a was linked to chemoresistance in the ribosome-inactivated cancer cells." (PMID 33972671, 2021). "Moreover, it has been reported that the direct contact of BM‐MSCs with cancer cells induces EMT and stem cell recovery of cancer cells via the paracrine actions of TGF‐β derived from BM‐MSCs, along with the autocrine action of Wnt‐5a secreted from cancer cells." (PMID 32724891, 2020). "Intriguingly, although Wnt5a regulates inflammatory processes in both infectious and inflammatory diseases, such as tuberculosis, sepsis, psoriasis, rheumatoid arthritis, and atherosclerosis, its role in inflammation in the context of cancer has been poorly investigated." (PMID 31510045, 2019). "Inhibition of APT1 may represent a novel way to treat Wnt5a driven cancers." (PMID 29648538, 2018). "Thus, whether Wnt5a suppresses or leads to cancer formation depends on the cell surface receptor it binds." (PMID 30079293, 2018). "However, the role of Wnt5a in cancer stem cells is varied and complex." (PMID 28491097, 2017). "Epigenetic mechanisms could also participate in the aberrant expression of WNT-5A in cancer cells." (PMID 26514730, 2016). "However, opposite effects were obtained for WNT5a in other types of cancer." (PMID 26958939, 2016). "Many studies have revealed that Wnt5a may drive chemotherapy resistance in different cancer types." (PMID 27571105, 2016). "Several lines of evidence have suggested that the Wnt/PKC signaling pathway was aberrantly activated in some cancer types, in which Wnt5a might activate this signaling and was responsible for metastasis and chemoresistance in cancers in part through activation of Wnt/β-cateinin signaling." (PMID 27895670, 2016). "In summary, we found that Wnt5a signal regulates invasion and proliferation of cancer cells through receptor-mediated endocytosis-dependent and -independent mechanisms, respectively, using our newly generated anti-Wnt5a neutralizing monoclonal antibody and labelled Wnt5a protein." (PMID 25622531, 2015). "In addition, it has been revealed that canonical Wnt signaling may be antagonized by Wnt5a in some types of cancer cells." (PMID 25779663, 2015). "However, the biologics of Wnt5a in human cancers are still unclear." (PMID 24999479, 2014). "However, the role of Wnt5a in cancer metastasis appears to be more complex." (PMID 24944588, 2014). "Furthermore, it is reasonable to hypothesize that Wnt5a and the involved signaling pathways may become molecular targets in the treatment of cancer metastasis." (PMID 24944588, 2014). "Previous studies have also described Wnt5a to increase fibroblast proliferation, increased inflammatory cytokine production and epithelial cell migration providing further insight into the molecular environment favoring fibrosis and cancer development in the elderly lung." (PMID 24981738, 2014). "It will be of high interest to determine which isoform of WNT5A exerts oncogenic functions in melanomas and gastric and pancreatic carcinomas, and monitoring the respective expression levels of WNT5A-L and WNT5A-S may be a useful cancer biomarker." (PMID 24260410, 2013).